GBP1 (guanylate binding protein 1)
Diseases named in the same sentence as GBP1 in open-access papers (continued):
Sharing a sentence is not in itself a finding about the gene and the disease.
brucellosis (1 paper, 2024). Brucellosis is a bacterial infection that spreads from animals to people via unpasteurized dairy products or by exposure to contaminated animal products or infected animals. "In brucellosis patients, the expression levels of many typical IFN‐γ/IFN‐I response genes, including IFITM3, B2M, GBP1, IRF1, IFI30, IFNGR2, and so forth, were higher than those in controls." (PMID 39135683, 2024).
Burkholderia Infections (1 paper, 2021). Infections with bacteria of the genus BURKHOLDERIA. "Although it has been reported that B. thailandensis is targeted by GBP1 in human epithelial cells, the role of GBPs during Burkholderia infection of human cells, and specifically epithelial cells, is largely unknown." (PMID 34399626, 2021). "Therefore, we speculated that one or several of these mechanisms might be responsible for the GBP1-dependent restriction of MNGC formation in human epithelial cell lines in response to Burkholderia infection." (PMID 34399626, 2021).
celiac disease (1 paper, 2022). An autoimmune genetic disorder with an unknown pattern of inheritance that primarily affects the digestive tract. "The most significantly up-regulated genes in celiac disease were TAP1, HLA-E, HCP5, STAT1, GBP1, STAT1, LOC100419583, and GBP4 and the down-regulated ones were IDS, PKIB, FBXO2, OXT, and ADI1." (PMID 36011206, 2022).
cervical adenocarcinoma (1 paper, 2024). An adenocarcinoma arising from the cervical epithelium. "In addition, immunohistochemical results of HPA database showed that GBP1 protein could be detected in both cervical adenocarcinoma and cervical squamous cell carcinoma, presenting low to high staining results." (PMID 38167153, 2024).
cervical squamous cell carcinoma (1 paper, 2024). A squamous cell carcinoma arising from the cervical epithelium. "TCGA data analysis showed that GBP1 was widely expressed in Cervical squamous cell carcinoma and endocervical adenocarcinoma (CESC) tissue, but did not have significant differences compared with normal tissue." (PMID 38167153, 2024).
colorectal tumor (1 paper, 2023). "To test whether this mechanism holds true at the tissue-level, we used IFNγ-responsive, patient-derived colorectal tumor organoids and tested if the GBP1:PIM1 interaction inhibitor NSC756093 affected cell viability, organoid growth and stemness." (PMID 37797010, 2023).
congenital hypothyroidism (1 paper, 2021). A thyroid hormone deficiency present from birth. "In summary, in this study, we found that GBP1 variations are a potential cause of thyroid dysgenesis and congenital hypothyroidism in patients." (PMID 34194003, 2021).
cutaneous squamous cell carcinoma (1 paper, 2025). "Prior studies have demonstrated that GBP1 interaction with SP1 promotes STAT3 activation, which enhances proliferation and invasion in cutaneous squamous cell carcinoma." (PMID 40975978, 2025).
encephalitis (1 paper, 2013). An acute inflammatory process affecting the brain parenchyma. "Surviving Gbp1−/− mice showed elevated CNS pathology consistent with encephalitis as the cause of death." (PMID 23633952, 2013). "The delayed death phenotype of Gbp1−/− mice is reminiscent of type II infection in Nos2−/− mice, which succumb due to encephalitis." (PMID 23633952, 2013).
endotoxemia (1 paper, 2018). "Interestingly, we found that GBP2 deficiency fails to significantly inhibit caspase-11-dependent immune responses in endotoxemia; whereas genetic deletion of GBP1, GBP2, GBP3, GBP5 and GBP7 simultaneously blocked endotoxemia-induced caspase-11 activation." (PMID 30587103, 2018).
hepatocellular carcinoma (1 paper, 2019). A malignant tumor that arises from hepatocytes. "In hepatocellular carcinoma, low expression of the GBP1 gene in the non-tumorous tissue of the remnant liver was reported to be associated with early recurrence after surgical resection." (PMID 31998647, 2019).
human papillomavirus infection (1 paper, 2024). "However, whether GBP1 can inhibit human papillomavirus infection is unclear." (PMID 38622605, 2024).
hypothyroidism (1 paper, 2021). Abnormally low levels of thyroid hormone. "Tshba transcripts, one of the most sensitive markers for hypothyroidism diagnosis, were increased in 5-dpf gbp1-deficient embryos compared with WT controls, as detected by reverse transcription PCR (RT-PCR)." (PMID 34194003, 2021). "This study also found that the deficiency of GBP1 increased the expression of E-cadherin and β-catenin in the membrane of thyrocytes to form the adhesion complex, leading to highly adhesive thyroid morphology and hypothyroidism in gbp1-deficient embryos." (PMID 34194003, 2021). "In zebrafish embryos, gbp1 knockdown caused defective thyroid primordium morphogenesis and hypothyroidism." (PMID 34194003, 2021). "The reduction in follicle numbers and thyroxine-containing units support the hypothesis that hypothyroidism develops with gbp1 deficiency." (PMID 34194003, 2021). "Using a zebrafish model organism, we demonstrated that GBP1 regulated TP morphogenesis and induced hypothyroidism might be mediated by suppression of β-catenin-dependent adhesion complex formation." (PMID 34194003, 2021).
latent infection (1 paper, 2014). "Moreover, we profiled the IRF4 transcriptome in the context of EBV latent infection, and confirmed several genes including IFI27, IFI44, GBP1, and ARHGAP18, as well as CFLAR as novel targets for IRF4." (PMID 25207815, 2014).
leprosy (1 paper, 2019). Leprosy is a chronic infectious disease affecting primarily the skin and peripheral nervous system. "GBP1, GBP2 and GBP5 are specific to the RR signature in comparison to the other clinical forms of leprosy." (PMID 31600201, 2019).
malaria (1 paper, 2013). Malaria is a serious and sometimes fatal disease caused by a parasite that commonly infects a certain type of mosquito which feeds on humans. "The expression levels of GBP1, GBP2, and TAP1 ranged from 10.6- to 2.8-fold above baseline during early stage of malaria, and the expression level of GBP2 was greater than two-fold change during acute febrile malaria." (PMID 24188121, 2013).
myelofibrosis (1 paper, 2022). A partial or complete replacement of the bone marrow stroma by fibrous tissue. "Therefore, these four genes (OAS1, IFITM3, GBP1, and GBP2), especially OAS1, might possess the potential to be novel auxiliary diagnostic and predictive indicators of myelofibrosis, but further research is still necessary in the future." (PMID 36061178, 2022). "Additionally, the four genes (OAS1, IFITM3, GBP1, and GBP2) we identified in this study might have the potential to be auxiliary diagnostic and predictive indicators of myelofibrosis, but further investigations are still necessary in the future." (PMID 36061178, 2022). "The results showed high AUC values of the four genes (OAS1, IFITM3, GBP1, and GBP2) when distinguishing JAK2V617F+ myelofibrosis from JAK2V617F+ PV or ET." (PMID 36061178, 2022). "The external datasets validated the upregulation of four interferon-related genes (OAS1, IFITM3, GBP1, and GBP2) in JAK2V617F+ myelofibrosis." (PMID 36061178, 2022). "Furthermore, we identified four potentially important genes (OAS1, IFITM3, GBP1, and GBP2) that were upregulated uniquely in myelofibrosis." (PMID 36061178, 2022). "Overall, the four interferon-stimulated genes (OAS1, IFITM3, GBP1, and GBP2) exclusively upregulated in myelofibrosis might not only provide important novel clues to the MPN field but also offer special insights into the effects of IFN signaling on the pathogenesis of myelofibrosis." (PMID 36061178, 2022).
neuroblastoma (1 paper, 2022). Neuroblastoma (NB) is the most common solid, extracranial childhood tumor. "Depletion of GBP1 in an IFNγ primed environment also inhibited virus replication in human neuroblastoma SH-SH5Y cells." (PMID 35663470, 2022). "A similar proviral role of GBP1 was also observed in human neuroblastoma SH-SY5Y cells." (PMID 35663470, 2022). "We further validated our results in JEV infected human neuroblastoma SH-SY5Y cells, where we observed significantly enhanced transcript levels of Gbp1, Gbp2, Gbp4 & Gbp5." (PMID 35663470, 2022).
non-small cell lung carcinoma (1 paper, 2021). A group of at least three distinct histological types of lung cancer, including non-small cell squamous cell carcinoma, adenocarcinoma, and large cell carcinoma. "GBP1 promotes chemoresistance via PGK1-activated EMT signaling in non-small cell lung cancer." (PMID 34439200, 2021).
nonalcoholic fatty liver disease (1 paper, 2023). "According to the existing research, GBP1 was repressed in hepatitis B virus‐infected patients, GBP2 expression levels were enhanced in patients with nonalcoholic fatty liver disease, and overexpression of GBP5 could induce liver injury and inflammation." (PMID 37551111, 2023).
Pan (1 paper, 2022). "Pan-cancer patients with higher GBP1 expression were more inclined to display “hot” anti-tumor immune phenotypes and had lower TIDE scores and higher immunophenoscore, suggesting that these patients had better responses to immunotherapy." (PMID 35222540, 2022).
pancreatic cancer (1 paper, 2017). "GBP1 expression is also linked to a lack of responsiveness to radiotherapy in some tumors, and GBP1 is overexpressed in pancreatic cancer that is refractory to oncolytic virus therapy." (PMID 29115931, 2017).
preeclampsia (1 paper, 2024). Preeclampsia is a hypertensive disorder of pregnancy that is characterized by new-onset hypertension with proteinuria presenting after 20 weeks of gestation, and depending on mild or severe forms may initially present with severe headache, visual disturbances, and hyperreflexia. "Similarly, GBP1 expression appears to increase with progressing healthy pregnancies, but this increase is attenuated in preeclampsia, associating reduced GBP1 expression, as reported by proteomics in this study, with an inflammatory placental environment." (PMID 38396626, 2024).
selenium deficiency (1 paper, 2012). A nutritional deficiency disease resulting from inadequate selenium levels in the body, which can lead to impaired function of selenoproteins essential for antioxidant defense and thyroid hormone metabolism. "Although selenium deficiency seemed to demonstrate a reduction in GBP-1 mRNA expression, dietary selenium did not have an effect on the protein expression of GBP-1 in Sep15−/− mice or Sep15+/+ littermate controls." (PMID 23226526, 2012).
ZIKV infection (1 paper, 2024). "A previous study identified GBP2/5, two GBP1-prenylation paralogs, to be upregulated upon ZIKV infection, thus leading to reduced viral replication through inhibition of the host protease furin." (PMID 38315728, 2024).
infection (91 papers, 2007 to 2026). The state of being infected such as from the introduction of a foreign agent such as serum, vaccine, antigenic substance or organism. "To rule out the presence of artifacts caused by this, we further compared the GBP1 expression after infection in Huh7 and Huh7.5 cells." (PMID 38315728, 2024). "To this end, we infected WT, Gbp1–/–, Gbp2–/–, Gbp3–/–, Gbp5–/–, and Aim2–/– mice with F. novicida and monitored their susceptibility to infection." (PMID 35906252, 2022). "The infection caused a large increase of Gbp2b/Gbp1 and Gbp5 expression, but Gbps levels in both uninfected and infected mice differ among mouse strains indicating influence of genetic factors." (PMID 29467757, 2018). "Infection resulted in approximately 10× upregulation of Gbp2b/Gbp1 and Gbp5 mRNAs in organs of both susceptible and resistant strains, which was most pronounced in skin." (PMID 29467757, 2018). "We infected 293T cells with this library, and combined FACS with super-infection by a GFP-encoding recombinant adeno-associated virus (rAAV) to isolate GBP1-TagBFP variants whose blue fluorescence depended upon GFP expression." (PMID 27205882, 2016). "To examine the role of Gbp1 in resistance to T. gondii, we first tested the ability of IFN-γ-activated BMM from Gbp1-deficient mice (Gbp1−/−) to clear parasites following overnight infection in vitro." (PMID 23633952, 2013). "Greater susceptibility was also seen in vivo, with Gbp1−/− mice succumbing to infection earlier with Δrop18 parasites, which are partially attenuated in virulence towards wild type mice." (PMID 23633952, 2013). "Collectively, these results demonstrate that Gbp1 plays an important role in the control of infection in vivo as Gbp1-deficent animals show increased susceptibility both during acute and chronic infection." (PMID 23633952, 2013). "Indeed, we observed rapid TgIST-dependent depletion of PIM1 upon infection with Tg, further precipitating the loss of GBP1 phosphorylation and interaction with 14-3-3σ." (PMID 37797010, 2023). "Notably, Tg infection in macrophages caused GBP1‐dependent apoptosis and STm infection led to GBP1‐dependent increase of pyroptosis." (PMID 31268602, 2019). "It has been shown that dendritic cells derived from the blood of healthy human donors expressed more GBP1 and GBP2 after infection with L. major promastigotes, whereas dendritic cells infected with L. donovani expressed more GBP1." (PMID 40100809, 2025). "Next, we compared the caspase activity in HIF1‐KD and GBP1‐KD after HN878 or CDC1551 infection with that in the uninfected, as well as infected control macrophages." (PMID 41287823, 2025). "Compared with the control, HIF1‐KD and GBP1‐KD macrophages had a significantly higher bacterial load upon infection with HN878 or CDC1551 at 48 and 96 h postinfection." (PMID 41287823, 2025). "Later during infection, at 12 dpi, the top ten significantly upregulated genes with highest fold change included, similar to 4 dpi, Zbp1, Oas2, Gbp1, Ddx60, Oas1a and Mx1." (PMID 38536871, 2024). "Our “open conformer” model provides a dynamic view into how the human GBP1 defense complex mobilizes innate immunity to infection." (PMID 38422126, 2024). "When compared to the control, the GBP1 mRNA levels were relatively upregulated from 3 to 24 h post-infection (hpi)." (PMID 36918936, 2023). "For example, the NS5B of HCV interacts with the GTPase domain of GBP1, hence blocking its GTPase activity and antiviral effect to ensure the persistent infection and intracellular replication of HCV." (PMID 36918936, 2023). "During infection with the cytosolic bacterium S. flexneri, in addition to GBP1, other GBPs are recruited to inhibit bacterial actin-based motility." (PMID 37737612, 2023). "GBP1P1 represents a pseudogene of guanylate-binding protein 1 (GBP1), which is responsible for autophagosome formation during intracellular pathogen infection." (PMID 37402153, 2023).
infection (continued). "Consistent with reduced IFNγ expression, the mRNA induction of Nos2, Gbp1, Gbp2, Gbp4, Gbp5, Ido1 and Acod1 was severely impaired in the spleens of Myd88−/− mice after intraperitoneal infection." (PMID 36479617, 2023). "These experiments showed that the activity of GBP1 is restrained in uninfected cells but can be rapidly triggered upon infection by a pathogen that interferes with IFNγ-signaling." (PMID 37797010, 2023). "GBP1, a distinctive large GTPase enzyme, regulates cellular reactions to infection, inflammation, and environmental stress." (PMID 37796192, 2023). "Herein, we demonstrate that mouse GBP1 (mGBP1) was upregulated in a mouse airway epithelial cell line (LA‐4 cells) following pretreatment with mouse IFNα or infection by influenza A virus (IAV)." (PMID 36744765, 2023). "GBP1 functions to elicit divergent host cell death programs in response to infection with intracellular pathogens, and increases access to PAMPs." (PMID 35720382, 2022). "As the results showed, the expression level of GBP1 was fairly high, and overexpression of GBP1 significantly suppressed FMDV replication in different infection times." (PMID 35937300, 2022). "GBP1 is a large gtpase of the dynamin superfamily governing cellular responses to infection, inflammation, and cancer." (PMID 35222540, 2022). "Gbp1–/– mice lost more body weight compared with WT mice and 72% of Gbp1–/– mice succumbed to infection within 7 days, whereas 88% of the WT mice survived." (PMID 35906252, 2022). "At the same time, we found that overexpression of GBP1 significantly inhibited the replication of FMDV at different infection time points." (PMID 35937300, 2022). "Use of high-throughput imaging assays and genome engineering allowed us to define a role for GBP1, 2 and 5 in parasite infection control." (PMID 34931666, 2022). "In summary, GBP1, 2 and 5 contributed to the control of Tg infection via parasite growth restriction and reduction of vacuole/cell numbers in three different human, in vitro macrophage models, including primary-like iPSCs and primary MDMs." (PMID 34931666, 2022). "To further assess the influence of GBP1, 2 and 5 in controlling Tg infection in macrophages, we next assessed THP-1 CRISPR knockout cell lines of the respective gene." (PMID 34931666, 2022). "Analysis of serum IL-18 showed that Gbp1–/– and Gbp3–/– mice had an impaired ability to produce this inflammasome-dependent cytokine following infection with F. novicida." (PMID 35906252, 2022). "Transcriptionally GBP1 (guanylate-binding protein 1) was found to be elevated at 48-h post-infection in HEV infected cells (A549) compared to UV inactivated HEV infection as well as in replicon transfected hepatocyte cell lines." (PMID 34502167, 2021). "Although GBP1 and GBP5 have been demonstrated to be highly associated with increased host resistance against infection with different PRRSV strains, the mechanisms of the increased host resistance to PRRS have not been characterized to date." (PMID 32075688, 2020). "Guanylate binding protein 4 (GBP4) and GBP1 were both induced following GII.4 infection of both organoid lines." (PMID 32184238, 2020). "We also found that compared with wild-type BMDMs, BMDMs from Irgb6-deficient mice displayed impaired T. gondii killing activity, increased infection rate, and reduced recruitment of Irgb10, Irga6, Gbp1, Gbp2, Gbp1-5, ubiquitin, and p62." (PMID 31852733, 2020). "The GBP-1 is 65 kD GTPase protein plays a crucial role in innate immunity as well as a prognostic biomarker for infection outcome." (PMID 32117813, 2020). "Guanylate-binding protein 1 (GBP1) was among the 30-top down-regulated genes after infection with L. infantum, which also appears to contribute to the suppression of inflammasome activation." (PMID 31961876, 2020).